STK11 (serine/threonine kinase 11)
Description:
Tumor suppressor serine/threonine-protein kinase that controls the activity of AMP-activated protein kinase (AMPK) family members, thereby playing a role in various processes such as cell metabolism, cell polarity, apoptosis and DNA damage response. Acts by phosphorylating the T-loop of AMPK family proteins, thus promoting their activity: phosphorylates PRKAA1, PRKAA2, BRSK1, BRSK2, MARK1, MARK2, MARK3, MARK4, NUAK1, NUAK2, SIK1, SIK2, SIK3 and SNRK but not MELK. Acts as a key upstream regulator of AMPK by mediating phosphorylation and activation of AMPK catalytic subunits PRKAA1 and PRKAA2 and thereby regulates processes including: inhibition of signaling pathways that promote cell growth and proliferation when energy levels are low, glucose homeostasis in liver, activation of autophagy when cells undergo nutrient deprivation, and B-cell differentiation in the germinal center in response to DNA damage. Also acts as a regulator of cellular polarity by remodeling the actin cytoskeleton. Required for cortical neuron polarization by mediating phosphorylation and activation of BRSK1 and BRSK2, leading to axon initiation and specification. Regulates UV radiation-induced DNA damage response mediated by CDKN1A. In association with NUAK1, phosphorylates CDKN1A in response to UV radiation and contributes to its degradation which is necessary for optimal DNA repair. [Isoform 2]: Has a role in spermiogenesis.
Synonyms: LKB1; hLKB1; PJS
Tractability: Small molecule: a structure with a bound ligand is known; a high-quality ligand is known; it has a binding pocket of medium quality; it belongs to a druggable protein family. PROTAC: its protein half-life has been measured; a small molecule that binds it is known.
Target class: Kinase; Protein Kinase; CAMK protein kinase LKB subfamily; Enzyme; CAMK protein kinase group; CAMK protein kinase CAMK1 family
Safety:
Unwanted effects reported when the protein is acted on. In parentheses: how it was acted on, where the effect was seen, and who reports it.
heart disease (cardiovascular system; source: Force et al. (2011))
Gene: Protein-coding gene on chromosome 19 (1,177,558 to 1,228,431, forward strand). Ensembl gene ENSG00000118046.
Subcellular location: Nucleus; Cytoplasm; Membrane; Mitochondrion; Late endosome; Nucleus (Isoform 2)
Subcellular location (Human Protein Atlas): Nucleoplasm; Centrosome; Cytosol; Primary cilium
Pathways (Reactome):
Gene expression (Transcription): FOXO-mediated transcription of cell death genes
Metabolism: AMPK inhibits chREBP transcriptional activation activity
Signal Transduction: Energy dependent regulation of mTOR by LKB1-AMPK
Gene Ontology:
Molecular function: ATP binding; magnesium ion binding; protein binding; protein kinase activator activity; protein serine kinase activity; protein serine/threonine kinase activity; LRR domain binding; protein kinase activity
Biological process: activation of protein kinase activity; anoikis; cellular response to UV-B; DNA damage response; establishment of cell polarity; G1 to G0 transition; negative regulation of canonical Wnt signaling pathway; negative regulation of cell population proliferation; negative regulation of TORC1 signaling; peptidyl-threonine phosphorylation; positive regulation of autophagy; positive regulation of transforming growth factor beta receptor signaling pathway; positive regulation of vesicle transport along microtubule; protein autophosphorylation; protein dephosphorylation; protein phosphorylation; cellular response to glucose starvation; glucose homeostasis; negative regulation of cell growth; negative regulation of cold-induced thermogenesis; regulation of cell cycle; regulation of cell growth; regulation of Wnt signaling pathway; and 3 more
Cellular component: cytoplasm; cytosol; extracellular exosome; intracellular protein-containing complex; mitochondrion; nucleoplasm; nucleus; serine/threonine protein kinase complex; late endosome; membrane
Genetic constraint (gnomAD): Loss-of-function variants: 8 observed, 39.66 expected, observed/expected ratio (o/e) 0.2, 90% interval 0.12 to 0.36. The synonymous counts are far from expectation, so gnomAD's model fits this gene poorly and the ratio says little. Missense variants: 475 observed, 572.96 expected, observed/expected ratio (o/e) 0.83, 90% interval 0.77 to 0.89. Synonymous variants: 330 observed, 248.23 expected, observed/expected ratio (o/e) 1.33, 90% interval 1.21 to 1.46.
Gene-disease validity (ClinGen):
ClinGen rates the evidence that STK11 causes each of these diseases.
Peutz-Jeghers syndrome (autosomal dominant): Definitive. An autosomal dominant disorder caused by pathogenic variants in the STK11 gene, characterized by hamartomatous polyps in the gastrointestinal tract, mucocutaneous pigmentation and increased risk of GI and extra-GI malignancies.
familial ovarian cancer (autosomal dominant): No Known Disease Relationship. An instance of ovarian cancer that is caused by an inherited modification of the individual's genome.
Cancer hallmarks: escaping immune response to cancer (suppresses); invasion and metastasis (suppresses); angiogenesis (suppresses); suppression of growth (promotes); escaping programmed cell death (suppresses); angiogenesis (promotes); change of cellular energetics; tumour promoting inflammation (suppresses); genome instability and mutations (suppresses); escaping immune response to cancer; tumour promoting inflammation
Homologues: Orthologues: macaque STK11 (99% identical), dog STK11 (93% identical), pig STK11 (93% identical), guinea pig STK11 (91% identical), mouse Stk11 (91% identical), rat Stk11 (84% identical), zebrafish stk11 (83% identical), tropical clawed frog stk11 (80% identical), chimpanzee STK11 (70% identical), Drosophila melanogaster Lkb1 (52% identical), Caenorhabditis elegans par-4 (39% identical). Paralogues in human: CAMKK2 (27% identical), DCLK1 (27% identical), DCLK2 (26% identical), CAMKK1 (25% identical), CAMK2B (24% identical), CAMK2G (24% identical), PSKH1 (24% identical), CAMK2D (22% identical), CAMK2A (22% identical), CAMK1D (22% identical), MYLK3 (22% identical), CAMK1 (21% identical), and 10 more.
Diseases named in the same sentence as STK11 in open-access papers:
STK11 is named in the same sentence as 431 diseases in open-access papers, as found by Europe PMC text mining. Sharing a sentence is not in itself a finding about the gene and the disease. The quoted sentences say what the papers report.
lung cancer (447 papers, 2008 to 2026). A malignant neoplasm involving the lung. "To assess the impact of KEAP1/STK11 mutations on immune profiles, we analyzed RNA-seq data from the TCGA lung cancer cohort and the GSE72094 cohort." (PMID 41378285, 2025). "In fact, it was recently shown that STK11-mutant lung cancer is associated with interferon gamma signaling in tumors with low infiltration of CD8+ T cells." (PMID 39995872, 2025). "To access the impact of KEAP1/STK11 mutations on immune landscape of lung cancer, we utilized two bulk RNA-seq datasets: TCGA-lung cancer and GSE72094, for our analysis." (PMID 41378285, 2025). "In lung cancer, suppression of inflammation genes has been reported in patients harboring STK11 and KRAS co-mutations." (PMID 41051525, 2025). "Despite strong preclinical rationale supporting the use of mTORC1/2 inhibition in STK11-deficient lung cancer, clinical activity of vistusertib was clearly disappointing, even in cancers with concomitant KRAS mutations." (PMID 40069402, 2025). "STK11/KRAS co-mutated lung cancer cells demonstrate increased glycolysis, and are more sensitive to glycolysis inhibition or glucose deprivation than either KRAS single mutant or STK11 single mutant cells." (PMID 40069402, 2025). "By 8 weeks resistant lung cancer nodules develop which are FDG avid, but these resistant nodules are not adenocarcinoma (the classic histological subtype of human STK11-deficient/KRAS mutant lung cancer) but squamous cell carcinoma." (PMID 40069402, 2025). "These proof of principle and mechanism studies demonstrate in a relevant lung cancer model a significant susceptibility of KRAS mutant/STK11 deficient lung adenocarcinoma to dual mTORC1/2 inhibition." (PMID 40069402, 2025). "The A549 nonsmall cell lung cancer line is widely used as a model for lung adenocarcinoma studies since it presents a high proliferative rate and a nonsense mutation in the STK11 gene." (PMID 39955067, 2025). "Cell line sensitivity data suggests that alternative clinical testing with everolimus is unlikely to change our conclusion that mTOR inhibition is of limited value in STK11-deficient lung cancer." (PMID 40069402, 2025). "The authors mentioned that this gene has been previously reported to be upregulated in cell lines with loss-of-function mutations in STK11, a major tumor suppressor gene in lung cancer." (PMID 40004528, 2025). "For example, co-mutation of KEAP1/STK11 was more common in patients with KRASG13-mutated lung cancer than in patients with KRASG12D-mutated lung cancer, and co-mutation of KEAP1/STK11 with KRASG13 was associated with poor prognosis and treatment resistance." (PMID 38310130, 2024). "STK11/LKB1 mutations are the main cause of primary resistance to PD-1 inhibitors in KRAS-mutant lung cancer." (PMID 39252322, 2024). "In lung cancer, STK11 loss causes a metastasis-like subpopulation of cancer cells in primary tumors and metastases to activate the early endodermal transcription factor, Sox17." (PMID 38461159, 2024). "Previous studies using inducible mouse models of Kras-driven lung cancer have reported Stk11 deficiency correlates with altered tumor-intrinsic cytokine expression." (PMID 37968341, 2024). "All of the 7 IRGs were significantly overexpressed in STK11-mutated lung cancer, both in the LUSC cohort and LUAD cohort." (PMID 38736875, 2024). "Genetic ancestry is associated with specific somatic driver mutations in EGFR, KRAS, and STK11 in lung cancer in individuals of Indigenous American ancestry relative to those of EUR or EAS ancestry." (PMID 38836758, 2024). "KEAP1 and STK11 mutations have been identified as associated with immunotherapy resistance in lung cancer." (PMID 39723373, 2024).
lung cancer (continued). "ALK rearrangement and STK11 gene mutation are also associated with VTE in patients with lung cancer." (PMID 38890693, 2024). "Based on studies reporting a correlation between Stk11 loss and Il-6 upregulation in mouse models of Kras-driven lung cancers in vivo, we compared IL-6 expression between STK11 WT (aka “Parent”) and matched STK11-KO human LUAD cells using qRT-PCR." (PMID 37968341, 2024). "In STK11-/Lkb1-deficient lung cancer, CB839 demonstrates a notable suppression of CD8 + T cells clonal expansion and activation." (PMID 38459595, 2024). "We performed a screen for tumour‐secreted cytokines and chemokines using mice carrying inducible KrasG12D/+ and Stk11/Lkb1flox/flox (KL) alleles, a well‐established genetically engineered mouse model that develops aggressive lung cancer." (PMID 37759102, 2023). "Loss of LKB1 due to mutations in STK11 contributes to cancer progression and resistance to certain therapies, making it a potential target for the development of more effective lung cancer treatments." (PMID 37444584, 2023). "Studies have reported that STK11 mutations bear some relation with poor prognosis in patients with cervical cancer, epithelial ovarian cancer, lung cancer, and so forth." (PMID 37506141, 2023). "In some cases, ENOB has been found to be highly expressed in STK11 mutant lung cancer and colorectal cancer, associated with poor patient outcomes." (PMID 37894372, 2023). "In this study, we used a genetic model of lung cancer driven by an activating mutation in Kras and loss of the tumor suppressor gene, Lkb1 (Stk11)." (PMID 35719965, 2022). "This case highlights that although only a small proportion of lung cancer diagnoses will be due to hereditary predisposition, STK11 germline carriers should be under close surveillance for early detection of lung cancer." (PMID 35543335, 2022). "DTYMK deletion reduced the dTDP pool and markedly suppressed lung cancer cell growth under serine/threonine kinase 11 (LKB1)-deficient conditions." (PMID 35903153, 2022). "It regulates cellular metabolism, apoptosis, autophagy, and STK11 mutation is associated with poor prognosis in lung cancer." (PMID 36248982, 2022). "In lung cancer, patients with STK11 mutations showed resistance to anti-PD-1 inhibitors, and deletions in CDKN2A were negatively correlated with T-cell markers in different cancer types." (PMID 36138075, 2022). "Most lung cancer cells harboring STK11/LKB1 mutations also lose their polarity, acquire stem cell-like properties, and resist the host’s immune system." (PMID 35165542, 2022). "Most STK11 missense mutations negatively impact upon the LKB1 protein activity, which then lead to alterations of cancer-associated metabolism, lung cancer initiation, differentiation, local progression and metastatic dissemination." (PMID 35281267, 2022). "Analysis of the Pan-Lung Cancer gene set by The Cancer Genome Atlas indicates that STK11 loss is positively correlated to KRAS mutations in adenocarcinoma, whereas loss of PTEN is associated with squamous cell cancers." (PMID 33652656, 2021).
lung cancer (continued). "Comprehensive genomic profiling has revealed the genetic landscape of lung cancer, identifying inactivating somatic STK11 gene mutations as a common event in NSCLC." (PMID 34142658, 2021). "Mutations of STK11 are more frequently found in lung cancer than loss of PTEN, indicating discrepancy in the molecular mechanism." (PMID 33652656, 2021). "Four samples contained both KEAP1 and STK11 mutations, which have been shown to indicate lung cancer patients." (PMID 34830758, 2021). "These functional mouse studies interpret the mutation profile from the Pan-Lung Cancer cohort, where loss to STK11 is predominantly occurs in adenocarcinoma, whereas loss of Pten is a rare event in the combination of activated Kras mutation." (PMID 33652656, 2021). "LKB1-inactivated KRAS mutant lung cancers harbor co-mutations in KEAP1 and/or significant co-occurrences of copy number loss in STK11/LKB1 and KEAP1 due to the chromosomal proximity of these genes." (PMID 34680229, 2021). "Based on this, the authors concluded that in KRAS-driven lung cancer, Stk11 mutations were essential for tumor progression." (PMID 34781949, 2021). "Mutation of liver kinase B1 (STK11), a tumor suppressor, increased exosome secretion in lung cancer." (PMID 33477340, 2021). "Traditionally genetically modified mice with conditional alleles for Stk11, Pten, and KrasG12D haven been applied to study lung cancer initiation and progression." (PMID 33652656, 2021). "Recent studies have reported that immune checkpoint inhibitors are less effective for lung cancers with STK11 mutations." (PMID 32887687, 2020). "While STK11 deletion or inactivating mutations are frequent in lung cancer (occurring in up to 50% of patients), STK11 mutations are rare in prostate cancer (0.2% incidence) and the frequency of STK11 deep deletion is also comparatively low (0–3.4% incidence)." (PMID 32630372, 2020). "Na+/K+ -ATPase was earlier investigated for treating STK11 mutated lung cancer cells by using CGs as therapeutic drugs." (PMID 32784680, 2020). "In contrast, restoration of liver kinase B1 (LKB1/STK11) expression, a tumor suppressor frequently mutated or lost in lung cancer, increases exosome secretion." (PMID 30925917, 2019). "Here, we report that targeting the Na+/K+-ATPase (ATP1A1) is synthetic lethal with STK11 mutations in lung cancer." (PMID 27431571, 2016). "For example, through a chemical library screen, Shackelford and colleagues found that LKB1 (STK11) deficient lung cancer cell lines were acutely sensitive to phenformin, an inhibitor of mitochondrial function." (PMID 27686855, 2016).